LEP (leptin)
Diseases named in the same sentence as LEP in open-access papers (continued):
Sharing a sentence is not in itself a finding about the gene and the disease.
endothelial dysfunction (continued). "Hypoxia, in turn, increases the production and release of proinflammatory cytokines, chemokines (MIP-1α and MCP-1), and leptin, inducing the infiltration of immune cells and decreasing local adiponectin production with consequent downregulation of NOS-3, thus favoring endothelial dysfunction." (PMID 33643076, 2021). "This indicates that reduction in leptin signaling but not fat mass promotes endothelial dysfunction in Tat-treated mice." (PMID 34681637, 2021). "In this study, the leptin and visfatin levels in plasma were increased, while ACh-induced endothelium-dependent vascular relaxation was significantly attenuated in CHF, which suggested the occurrence of endothelial dysfunction in CHF rats." (PMID 34422210, 2021). "In this regard, it is no surprise that factors such as oxidative stress, endothelial dysfunction, and leptin dysregulation can be indicators for OA lesion." (PMID 31121997, 2019). "The content of the circulating adhesion molecule vCAM-1 was positively correlated with the levels of CRP (r = 0.42), leptin (r = 0.31), TNF-a (r = 0.35) and IL-6 (r = 0.52), indicating the participation of proinflammatory molecules in the formation of endothelial dysfunction (p < 0.05)." (PMID 30871567, 2019). "Adipokines are involved in glucose metabolism (e.g., adiponectin, leptin, resistin, visfatin, and PAI-1), inflammation (e.g., resistin and leptin), reducing inflammation (e.g., adiponectin), coagulation (e.g., PAI-1), endothelial dysfunction (e.g., PAI-1), and feeding behavior (e.g., leptin)." (PMID 28552966, 2017). "In adiposity, excess secretion of various pro-inflammatory cytokines, chemokines, and proteases, such as TNF-α, IL-6, MCP-1, leptin, and PAI-1, by infiltrating macrophages and T cells around the adipose tissue, leads to endothelial dysfunction, oxidative stress, and inflammation activation." (PMID 28182687, 2017). "There are however no data available in the literature on the impact of leptin on markers of endothelial activation during pregnancy, despite the proposed link between adiposity and endothelial dysfunction." (PMID 24167814, 2013). "Unlike adiponectin, leptin was shown to have the ability to stimulate platelet activation and smooth muscle cell proliferation as well as to induce inflammation, oxidative stress, and endothelial dysfunction." (PMID 39335491, 2024). "al. showed that endothelial dysfunction in ob/ob mice can be reversed by leptin replacement and could therefore not be excluded as an contributor to the observed micorvascular dyfunction in this study." (PMID 26098416, 2015). "Though there are studies which show the mechanism of leptin based on NOS3 uncoupling, we hypothesized that the proinflammatory role of hepatic leptin might be crucial for endothelial dysfunction by up regulating miR21, a microRNA that has a pronounced role in inflammation." (PMID 25658689, 2015).
lipodystrophy (169 papers, 2004 to 2026). A congenital or acquired disorder characterized by abnormal loss or redistribution of the adipose tissue in the body. "Leptin deficiency with resultant hyperphagia coupled with inadequate fat storage results in metabolic complications of lipodystrophy." (PMID 39944202, 2025). "Metreleptin is a form of leptin replacement therapy used with diet and lifestyle modifications to treat the metabolic complications of leptin deficiency in lipodystrophy, a rare disease characterized by adipose tissue deficiency." (PMID 40469440, 2025). "Conversely, low leptin levels can be observed in conditions such as anorexia nervosa, malnutrition, and certain forms of lipodystrophy, highlighting the hormone’s role in energy deficiency states." (PMID 40152811, 2025). "In children and adults with lipodystrophy, which is associated with severe hypoleptinemia, recombinant leptin has metabolic benefits including reductions in hepatic fat content, fasting glucose, HbA1c, ALT, AST, and triglyceride levels." (PMID 40944251, 2025). "Recombinant methionyl human leptin (metreleptin) therapy is used together with diet to treat complications caused by leptin deficiency in people who have lipodystrophy." (PMID 40415699, 2025). "Leptin deficiency is a well-established hallmark of infertility resulting from lipodystrophy, and leptin add back often restores fertility in other lipodystrophic mouse models." (PMID 41206127, 2025). "Of note, restoring adipose endocrine function via leptin replacement has been shown to reverse lipodystrophy-associated metabolic dysfunction." (PMID 38811804, 2024). "Adipose tissue loss in lipodystrophy causes ectopic accumulation of fat in organs such as the liver and muscles and can result in low levels of circulating leptin — a key adipokine regulator of satiety and energy homeostasis." (PMID 38992753, 2024). "Hyperphagia is a leading symptom in lipodystrophy which can be more severe in GL due to absolute deficiency of leptin." (PMID 38183080, 2024). "Recent data has demonstrated a clear correlation between altered leptin and adiponectin secretion and the clinical features of congenital lipodystrophy, particularly in cases of generalized sWAT loss, which is more metabolically severe." (PMID 38951919, 2024). "Metreleptin is marketed as a leptin analogue, it was approved by the FDA in the year 2014 as a substitute to deficient leptin in patients with lipodystrophy." (PMID 38715796, 2024). "Metreleptin, a recombinant analog of human leptin, is an approved therapy, adjunct to diet, to treat the metabolic complications of leptin deficiency in patients with lipodystrophy – a group of rare diseases characterized by a paucity of adipose tissue." (PMID 37237416, 2023). "In this regard, situations of leptin deficiency, such as lipodystrophy, are related to lipid accumulation in ectopic organs, such as the liver." (PMID 36674935, 2023). "Nevertheless, the only approved therapeutical application for leptin is the control of metabolic complications in patients with genetic leptin deficiency or in patients with severe adipose tissue restriction (lipodystrophy)." (PMID 37024989, 2023). "The loss of leptin leads to severe metabolic disturbances, which include extreme hyperphagia, lipodystrophy and hypothalamic amenorrhoea." (PMID 34815532, 2022). "This study showed significant improvement in metabolic abnormalities linked to lipodystrophy and low baseline leptin levels, registered both in the short (1 year) and long term (mean, 5 years), with the overall result of patients’ quality of life amelioration." (PMID 35600578, 2022). "The goal of the present study is to analyze the effects of lipodystrophy and leptin deficiency on vascular contractility in the Bscl2 deficient mouse, a unique mouse model of congenital generalized lipodystrophy (CGL)." (PMID 34638939, 2021).
lipodystrophy (continued). "Since lipodystrophy is associated with low leptin and adiponectin levels, serum leptin and adiponectin levels were also measured." (PMID 34764936, 2021). "Lipodystrophy is associated with an increase in arterial cross-sectional area (CSA) which remains elevated under chronic leptin treatment in gBscl2-/- mice." (PMID 34638939, 2021). "For example, in addition topatients with lipodystrophy and those with insulin-deficient diabetes, which patients will benefit from leptin therapy?" (PMID 33167521, 2020). "Currently, leptin replacement therapy is being used successfully for the treatment of congenital leptin deficiency, leptin deficiency in lipodystrophy patients and hypothalamic amenorrhea only." (PMID 32069871, 2020). "Another pathophysiological leptin deficient state that can benefit from leptin replacement is lipodystrophy with good results improving glycemic control and decreasing triglyceride levels." (PMID 32824322, 2020). "Activation of the classical complement pathway and low C4 complement levels have been associated with low leptin and adiponectin levels and with destruction of adipocytes and lipodystrophy in patients with AGL." (PMID 29704234, 2019). "Recombinant leptin is already available for use in patients with leptin congenital deficiency while the synthetic leptin analog metreleptin has been approved for lipodystrophy treatment." (PMID 29910742, 2018). "Leptin deficiency, which correlates with the decreased amount of body fat, was shown to contribute to metabolic complications of lipodystrophies, whatever their underlying molecular mechanisms, both in mice and humans." (PMID 29578370, 2018). "In contrast, leptin replacement therapy has been shown to result in a significant improvement of the metabolic abnormalities associated with lipodystrophy (including a decrease in IMCL and IHCL)." (PMID 27649157, 2016). "Leptin, an adipokine involved in hunger-satiety pathways, is generally reduced, with a greater degree of leptin deficiency associated with complications from lipodystrophy." (PMID 41476924, 2025). "Further explorations might also consider a combination of leptin and adiponectin administration in rescuing lipodystrophy-associated metabolic cardiovascular diseases in Seipin/Apoe dKO mice." (PMID 38525541, 2024). "Moreover, leptin replacement therapy effectively corrects systemic metabolic dysfunction associated with lipodystrophy in mice and humans." (PMID 38811804, 2024). "One of the most striking aspects of the Mfn2R707W-associated lipodystrophy phenotype is the low or undetectable serum leptin concentration despite abundant whole body adiposity, accounted for mostly by excess upper body adipose tissue of relatively normal histological appearance." (PMID 36722855, 2023). "Furthermore, adipocytes from old Adipo-MDM2-KO showed remarkable and progressive loss of SWAT, eWAT, and BAT, and leptin and adiponectin levels were nearly undetectable, revealing an early onset of lipodystrophy in this mice model." (PMID 36354755, 2022). "Likewise, recombinant leptin and metreleptin (leptin analog), administered for lipodystrophy and congenital leptin deficiency, have been reported to reverse hepatic lipid accumulation and reduce the consequences of NASH." (PMID 33671547, 2021). "The lipodystrophies are a heterogeneous group of relatively uncommon disorders in which low leptin levels result from deficient mass of adipose tissue, the normal source of circulating leptin." (PMID 30357355, 2019). "We therefore studied leptin, IL-6 and suPAR that we hypothesised would be associated distinctively with lipodystrophy, adiposity and sarcopenia." (PMID 26244048, 2015). "Our objective was to study whether leptin, interleukin 6 (IL-6), and soluble urokinase plasminogen activator receptor (suPAR) were associated distinctively with adiposity, lipodystrophy and sarcopenia, in HIV-infected patients and healthy Controls." (PMID 26244048, 2015).
lipodystrophy (continued). "Thus we found leptin, IL-6 and suPAR to be associated with lipodystrophy, adiposity and sarcopenia distinctively." (PMID 26244048, 2015). "Our aim was therefore to study whether leptin, interleukin 6 (IL-6), and soluble urokinase plasminogen activator receptor (suPAR) were associated distinctively with adiposity, lipodystrophy and sarcopenia, in HIV-infected patients and healthy Controls." (PMID 26244048, 2015). "Notably, leptin or adiponectin therapy alone cannot fully reverse lipodystrophy-associated metabolic abnormalities, which might translate into a limited impact on cardiovascular phenotypes." (PMID 38525541, 2024). "The circulating leptin and adiponectin levels of our patient were significantly lower than those of other females in her family, reflecting fat loss, which may be one of the principal mechanisms by which lipodystrophy triggers insulin-resistant diabetes." (PMID 31293201, 2019). "While current lipodystrophy treatments primarily focus on enhancing leptin signaling, other investigational approaches are being explored." (PMID 40892266, 2025). "Therapeutic interventions, such as leptin replacement therapy, have demonstrated potential in the treatment of congenital leptin insufficiency and lipodystrophy while also enhancing glycaemic control, lipid profiles, and neuroendocrine function." (PMID 39931847, 2025). "These developments collectively provided the rationale to initiate a clinical trial testing the efficacy of leptin replacement strategy in severe lipodystrophy." (PMID 40892266, 2025). "Humans and rodents with lipodystrophy have diminished and dysfunctional adipose tissue and consequently produce little leptin." (PMID 40393800, 2025). "Leptin replacement therapy's role in the management of lipodystrophy has long been established, based on in vivo studies and small clinical trials." (PMID 39935494, 2025). "Metreleptin, a human leptin analog, is the only approved treatment for lipodystrophy in the United States." (PMID 40892266, 2025). "It has been previously shown that levels of triglyceride-rich lipoprotein particles are increased in lipodystrophy and that this atherogenic lipid profile improves after exogenous leptin therapy." (PMID 40520449, 2025). "Metreleptin improves glycaemic metabolism in patients with both partial and generalized lipodystrophy, particularly those with undetectable leptin levels." (PMID 40415699, 2025). "Leptin was positively correlated with AOM distance in patients with lipodystrophy (r = .513, P < .001)." (PMID 39352627, 2025). "It is widely recognized that leptin replacement improves hypertriglyceridemia in lipodystrophy, thereby preventing further episodes of pancreatitis." (PMID 39352627, 2025). "Other research has demonstrated broad clinical effects of metreleptin in lipodystrophy, supporting a pleiotropic role of leptin." (PMID 40842493, 2025). "Patients with lipodystrophy often have low concentrations of leptin in circulation, and leptin replacement therapy is used to manage metabolic dysfunctions associated with leptin deficiency and hyperphagia." (PMID 40663389, 2025). "Leptin treatment only works in individuals with initially low leptin concentration and in the case of lipodystrophy." (PMID 39057043, 2024). "If a few reports described pregnancy in patients with lipodystrophy, a minority of them reported leptin levels during pregnancy." (PMID 39479521, 2024). "Reduced leptin secretion contributes to the pathogenesis of lipodystrophy by adversely affecting appetite control, glucose and lipid homeostasis and metabolism." (PMID 38952397, 2024). "The regulation of leptin secretion during pregnancy and its potential therapeutic modulation in different phenotypes of lipodystrophy should be further investigated." (PMID 39479521, 2024).
lipodystrophy (continued). "While leptin deficiency is a hallmark in the pathology of lipodystrophy syndromes, consensus among the group was that a given leptin level cannot be used to rule in or out a lipodystrophy diagnosis." (PMID 38952397, 2024). "Metreleptin, a 16 kDa recombinant analog of human leptin administered via subcutaneous injection, is the only medical therapy specifically approved for the treatment of the metabolic complications of lipodystrophy." (PMID 38992753, 2024). "(2020) observed increased GDF-15 levels in mice with lipodystrophy, which decreased after treatment with leptin." (PMID 39420932, 2024). "Further evidence supporting the protective role of leptin in cardiovascular disease has been presented in studies involving patients with lipodystrophy." (PMID 38397015, 2024). "Long-term studies in children with lipodystrophy on the use of therapy with a methionylated human leptin analogue, metreleptin, have showed great improvements in the clinical situation and metabolic circumstances of these patients." (PMID 36674935, 2023). "As a result, a study has shown that metreleptin administration in female patients with lipodystrophy leads to an increased satiety time and a decrease in circulating ghrelin levels, supporting the important role of leptin in the regulation of human appetite." (PMID 37239098, 2023). "A characteristic feature of lipodystrophy is the decrease in levels of adipose tissue-derived hormones, such as leptin, and many derangements of lipodystrophies are corrected by leptin therapy." (PMID 37782317, 2023). "Leptin modulates food intake, satiety, and energy balance through its action on hypothalamic neurons; therefore, low levels of leptin in lipodystrophy can trigger hyperphagia." (PMID 37501786, 2023). "In the last decade, treatment with exogenous leptin has gained more attention in the therapeutic management of lipodystrophy." (PMID 37239098, 2023). "In monogenic insulin-resistant diabetes, subcutaneous leptin therapy is beneficial in some severe lipodystrophy." (PMID 35618782, 2022). "Given the cost of leptin, it is suggested that treatment should only be started in liaison with specialised lipodystrophy services, where accessible." (PMID 35618782, 2022). "Five weeks-HFD feeding leads to a more severe lipodystrophy and a more marked metabolic phenotype characterized by hyperglycemia, hyperinsulinemia, elevated TG and low adiponectin and leptin levels." (PMID 35250856, 2022). "Available data on adiponectin indicate that ART and in particular the treatment with IPs (ritonavir), lowers the levels of adiponectin and leptin especially at the beginning of therapy and favors the progression of lipodystrophy, steatosis and IR." (PMID 35355551, 2022). "Namely, we used ob/ob mice and Lepmkyo/Lepmkyo rats, which are leptin deficient obese models, and A-ZIP/F-1 mice and seipin KO (SKO) rats, which are models of generalized lipodystrophy." (PMID 35013417, 2022). "Mitigating this drive to eat is likely to be the main reason for efficacy of recombinant human leptin injection in lipodystrophy when baseline leptin concentration is particularly low." (PMID 35618782, 2022). "Studies on animals validated the role of adipose tissue in the pathogenesis of metabolic complications of lipodystrophy, all supporting and confirming the role of leptin therapy in improving the metabolic parameters." (PMID 35600578, 2022). "Specifically, a small cohort of nine patients with severe lipodystrophy (eight patients with GL and one patient with PL) and baseline serum leptin level of less than 4 ng/ml received the first dose of leptin." (PMID 35600578, 2022). "Consistent with the marked lipodystrophy, Aα4KO mice showed >89% decreases in circulating leptin levels." (PMID 36241662, 2022).